AR (androgen receptor)
Diseases named in the same sentence as AR in open-access papers (continued):
Sharing a sentence is not in itself a finding about the gene and the disease.
breast carcinoma (continued). "In conclusion, with the maintrac platform we are able to identify CETCs in patients with breast cancer and to determine AR expression on those cells." (PMID 30547831, 2018). "This highlights one of the pressing issues with clinical trials evaluating AR targeted therapies in breast cancer." (PMID 30416486, 2018). "A compendium of clinical trials either currently active or recruiting which target AR in breast cancer." (PMID 30416486, 2018). "The results revealed that the expression of AR was significantly associated with let-7a and CD44+/24-/low especially in estrogen receptor positive (ER+) breast cancer tissues." (PMID 29423076, 2018). "Nevertheless, in hormone receptor positive advanced breast cancers there is a significant proportion of patients who respond favorably to anti-AR therapy." (PMID 30416486, 2018). "And the effects of AR/let-7a signalling on the stem-like behavior of breast cancer cells are also evaluated in vitro and in vivo." (PMID 29423076, 2018). "Most reports indicating that AR is overexpressed in breast cancers are concluded based on immunohistochemical staining." (PMID 30279965, 2018). "Studies suggest AR play an important role in breast cancer development, in part via the role of let-7 up-regulation induced by AR activation." (PMID 29423076, 2018). "Androgen receptor (AR) is emerging as an important mediator in the biology and therapy of breast cancer (BC)." (PMID 29587674, 2018). "AR-positive patients, including female breast cancer and triple-negative breast cancer patients, respond to endocrine therapy and have better prognoses." (PMID 30577860, 2018). "A study has shown that when the AR in MDA-MB-453 breast cancer cells is knocked down, the cell colony formation rate is significantly decreased, which verifies the fact that the AR regulates the biological behavior of MABC." (PMID 29699584, 2018). "Clinically, comparison of primary vs. recurrent AI treated breast cancer samples by immunohistochemistry showed increased AR expression with concomitant decrease in ER and PR expression." (PMID 30416486, 2018). "Six patients who were treated with abiraterone had androgen receptor (AR) protein expression that ranged from 40% to 100%, including three patients with breast cancer, one patient with hepatocellular carcinoma, and one patient with bladder cancer." (PMID 32914004, 2018). "To assess the subtype distribution of AR expression across human breast cancers, we interrogated The Cancer Genome Atlas containing RNA-Seq data from 1246 invasive human breast cancer samples." (PMID 30279965, 2018). "In this respect, a genome‐wide approach has been applied to identify a network of the androgen receptor (AR)‐co‐expressed genes in breast cancer and to discover novel AR target genes and coregulators." (PMID 29577611, 2018). "Studies have stated that AR antagonists are able to induce breast cancer cell apoptosis and decrease tumor proliferation significantly in TNBC cell lines." (PMID 29699584, 2018). "The Androgen Receptor (AR) has recently garnered a lot of attention as a potential biomarker and therapeutic target in hormone-dependent cancers, including breast cancer." (PMID 30279965, 2018). "As a member of the nuclear receptor family, the androgen receptor (AR) plays an important role in breast cancer, and has been identified as a biomarker for a specific molecular subtype of breast cancer." (PMID 29699584, 2018). "MCF7 breast cancer cells overexpressing AR have shown increased resistance to AI therapy compared to non-overexpressing cells." (PMID 30416486, 2018). "Expression of the AR protein level was confirmed in an additional multi-institutional cohort of 197 breast cancer patients, for a total of 1258 patient evaluated." (PMID 29912871, 2018). "Despite the high frequency of AR expression in breast cancer its appraisal remains controversial because its role is complex, dependent on the hormonal milieu." (PMID 30547831, 2018).
breast carcinoma (continued). "Further investigation into AR expression reveals that only two major isoforms are expressed in human breast cancers, with both isoforms showing a significantly lower level of expression in the TNBC subtype compared to both other subtypes." (PMID 30279965, 2018). "The role of forkhead-box A1 (FOXA1) and Androgen receptor (AR) in breast cancer (BC) has been extensively studied." (PMID 29970021, 2018). "Androgen receptor (AR) is known to be a tumor suppressor in ER+ breast cancer type is one of the predictor belonging to cluster G and is not expressed in ER+ cells but expressed in BC07LN (metastasized triple negative TNBC cells)." (PMID 29433432, 2018). "Six patients, including three patients with breast cancer, were treated with abiraterone on the basis of androgen receptor protein overexpression." (PMID 32914004, 2018). "Conversely, AR has been shown to drive breast cancer cell growth in molecular apocrine tumors (triple negative, AR+ve)." (PMID 30416486, 2018). "Anti-AR therapy for the treatment of breast cancer is a very exciting field and we wait in hopeful anticipation for the emergence of more clinical trial data." (PMID 30416486, 2018). "Our group indicated that AR imported into the nucleus and up-regulated let-7a expression by binding to the androgen response elements of let-7a promoter region in breast cancer cells, upon androgen activation." (PMID 29423076, 2018). "AR antagonists bicalutamide (AstraZeneca) and enzalutamide (Medivation) are approved for metastatic prostate cancer, and are being tested in breast cancer." (PMID 29382369, 2018). "The aim of the current study was to investigate the frequency of AR and ER positive CETCs in breast cancer patients." (PMID 30547831, 2018). "The addition of AR to the classical triad biomarkers for breast cancers, particularly TNBCs, appears to add a prognostic benefit for clinicians to determine which tumors will be non-aggressive or aggressive." (PMID 29912871, 2018). "Collectively, these findings indicate that SRARP is highly co‐expressed with AR in breast cancer and has transcriptional regulatory effects on AR and ER signaling." (PMID 29577611, 2018). "In conclusion, our findings indicated that DHT-induced AR activation played a critical role in breast cancer, which was not only correlated with let-7a expression, but also related to BT-IC." (PMID 29423076, 2018). "Testosterone treatment induces both CXCL12 and CXCR4 expression in ER+ve breast cancer cells but only if AR and SRC1 are co-expressed." (PMID 30416486, 2018). "Androgen receptor (AR) is the most widely expressed steroid receptor protein in normal breast tissue and is detectable in approximately 90% of primary breast cancers and 75% of metastatic lesions." (PMID 30416486, 2018). "The purpose of our study was to better characterize AR and ER expression on CETCs in breast cancer contributing a new biomarker for targeted AR therapy, especially in patients with tamoxifen resistance." (PMID 30547831, 2018). "Secondly, the data presented in this paper also demonstrated widespread expression of both the AR and GR across breast cancer subtypes." (PMID 29563635, 2018). "This suggests the involvement of other sex steroids and/or their receptors such as the most abundantly expressed nuclear receptor in breast cancer, AR." (PMID 30416486, 2018). "In clinical cohorts heterogeneity of AR expression combined with ERα status appears to be the criteria influencing prognostic and predictive roles of AR in breast cancer." (PMID 30416486, 2018). "Many studies have centered upon the potential role of AR, however, due to its ubiquitous presence within breast cancers this is proving to be challenging." (PMID 30416486, 2018). "Androgen receptor (AR) is widely expressed in breast cancer (BC) but its role in estrogen receptor (ER)-positive tumors is still controversial." (PMID 29587674, 2018).
breast carcinoma (continued). "Androgen receptor and SRARP are highly co‐expressed in breast cancer and there are high levels of SRARP expression in AR+ breast cancer cell lines T‐47D and MFM‐223." (PMID 29577611, 2018). "We examined the gene and protein expression of AR in several human breast cancer cell lines using real-time PCR and Western blot analyses." (PMID 29713287, 2018). "Although is not completely clear the influence of circulating androgens in breast cancer development, the role of AR in BC progression seems to be undeniable." (PMID 30210453, 2018). "Currently there are ~16 active/recruiting clinical trials of drugs targeting the AR in the treatment of breast cancer across various subtypes." (PMID 30416486, 2018). "For example, the androgen receptor (AR) and the estrogen receptor (ER) β seem to promote male breast cancer, whereas both sex hormone receptors seem to inhibit female breast cancer." (PMID 30158439, 2018). "Increased expression, nuclear localization and/or phosphorylation of AR have now been observed in a few various breast cancer subtypes." (PMID 30279965, 2018). "In general, the majority of clinical trials are exploring AR antagonists as a therapeutic option for breast cancer." (PMID 30416486, 2018). "AR activation can inhibit estrogen-stimulated proliferation, and AR-induced cell apoptosis is also detected in ER+ breast cancer cells." (PMID 29423076, 2018). "To determine the expression of AR and its relationship to breast cancer subtypes, we compiled a series of Gene Expression Omnibus (GEO) profiles that contained racial and clinical outcomes data totaling 1061 patients." (PMID 29912871, 2018). "First, the ER factor is associated with both mRNA and protein expression of ESR1, AR and PR, and is enriched for gene signatures of ESR1 expression and the luminal subtype of breast cancer, which, in turn, is characterized by ESR1 overexpression." (PMID 30379847, 2018). "Here, we describe recent findings on AR in breast cancer with a renewed interest in elucidating the role of sex steroids and their metabolites in disease progression." (PMID 30416486, 2018). "Further studies are required in order to identify the miRNAs, including miR-9, miR-17-5p, miR-135a, and miR-449a, that contribute to KCa1.1 translational repression via mRNA degradation in AR-overexpressing breast cancer tissues." (PMID 29713287, 2018). "The androgen receptor (AR) is expressed in the majority of breast cancers and across the main breast cancer subtypes." (PMID 30547831, 2018). "There is still much debate surrounding nuclear receptor transcription mechanisms and some contrasting results between AR chromatin binding in breast cancer cell lines vs. human tissues have recently been published." (PMID 30416486, 2018). "Since AA women typically have the most aggressive forms of breast cancer, there is a need to measure the expression of AR in AA patients across all breast cancer subtypes and determine its relationship to clinical outcomes, particularly in TNBC-QNBC patients." (PMID 29912871, 2018). "Breast cancer is classified according to immunohistological detection of protein markers, including receptors for estrogen (ER), progesterone (PR), androgen (AR), and the amplified HER2 (Human Epidermal Growth Factor Receptor 2) receptor." (PMID 29615116, 2018). "AR is expressed in most breast cancers and has been proposed as a therapeutic target for triple negative breast cancer and breast cancer with drug resistance." (PMID 29713287, 2018). "In ERα-ve breast cancer Her2 overexpression impacts AR signaling, particularly in molecular apocrine breast cancer." (PMID 30416486, 2018). "It has been shown in prostate and breast cancers that activation of AR can be achieved also by ligand-independent signaling through crosstalk with other molecular signaling pathways, as a consequence of activation of the downstream PI3K/AKT/mTOR." (PMID 29731997, 2018).
breast carcinoma (continued). "In summary, we immunolocalized ARHGAP15 and Rac GAP in human breast carcinoma tissues, and ARHGAP15 immunoreactivity was significantly correlated with AR LI, decreased risk of recurrence, and better prognosis for the patients." (PMID 29534468, 2018). "We found that androgen-induced AR activating signal affects cells behavior both in ER+AR+ breast cancer cells, and also in ER-AR+ breast cancer cells." (PMID 29423076, 2018). "In recent years AR has attracted a great deal of attention in the management of breast cancer, because it turned out that AR is expressed in about 80% of breast cancers depending on the subtype, often at a higher level than ER." (PMID 30547831, 2018). "Prostate cancerdevelopment relies on the androgen receptor (AR), whereas breast cancer developmentprimarily relies on the estrogen receptor (ER)." (PMID 29162647, 2018). "At present, few are known on the relationship among AR, let-7a and the self-renewing BT-IC in breast cancer, and also their interactions." (PMID 29423076, 2018). "These insights into the AR signaling pathway will provide novel mechanisms for functional KCa1.1 regulation in breast cancer cells." (PMID 29713287, 2018). "Early in vitro studies have tried to elucidate the complex relationship between AR and ER expression and the variable responses to hormones and their antagonists in breast cancer cells." (PMID 28245550, 2017). "Cox regression analyses were performed to further investigate CBCM in relation to AR status, as well as to ER status and time from diagnosis to breast cancer-related death." (PMID 28643022, 2017). "Recently, a phase II trial of bicalutamide, an androgen antagonist, has shown a clinical benefit rate of 19% in a select group of patients with ER/PgR-negative, AR-positive breast cancer." (PMID 28915596, 2017). "Breast cancer cell lines with molecular apocrine features showed a significant functional cross-talk between AR and HER2 that involved FOXA1 activity." (PMID 29137314, 2017). "TRIM24 was reported as an oncogenic transcription factor in ER-driven breast cancer and AR-driven prostate cancer." (PMID 29129908, 2017). "Several lines of clinical data support the biologic importance of AR-signaling in breast cancer, although AR positivity has been found to have variable prognostic impact across studies." (PMID 28085048, 2017). "Studies conducted by my group and others have revealed that AR as a transcription factor has an important function in the regulation of key signaling pathways in breast cancer." (PMID 28915724, 2017). "Androgens play a role in breast cancer and several studies showed that the androgen receptor expression in ER-negative tumors can induce proliferative effect and promote tumorigenesis." (PMID 29100362, 2017). "Collectively, these findings suggest that C1orf64 and SPDEF are direct transcriptional targets of AR in breast cancer." (PMID 28915724, 2017). "Identification of TNBC subtypes such as lymphocyte predominant and luminal androgen receptor yields promise for personalized medicine in this aggressive type of breast cancer." (PMID 28893315, 2017). "Androgen receptor (AR) is present in almost 60–70% breast cancers and can play a role as a marker for breast cancer along with ER and PR." (PMID 29187162, 2017). "AR-positive breast cancer cell lines were treated with 4 Gy of ionizing radiation and AR RNA and protein levels were evaluated at 1, 12, 24, and 48 h after radiation treatment." (PMID 28840192, 2017). "A 19% clinical improvement was observed with bicalutamide over six months in a select group of patients with ER/PR-negative, AR-positive breast cancer." (PMID 28474005, 2017). "It should be noted that in addition to LAR tumors, other ER-negative, AR-positive breast cancer subtypes are sensitive to the effects of androgens." (PMID 28085048, 2017).
breast carcinoma (continued). "The increase in clinical trials with androgen receptor (AR)-targeting drugs emphasizes the need of clarifying the role of AR expression in different breast cancer subtypes." (PMID 28643022, 2017). "AR is a promising primary target for treatment in ER− breast cancer and especially in TNBC, where treatment options are scarce." (PMID 28643022, 2017). "In regards to AR activity in breast cancer carcinogenesis, multiple in vitro studies using several laboratory breast cancer cell lines (i.e., MCF-7, T47-D, and BT20) have shown an anti-proliferative effect of AR antagonism." (PMID 28245550, 2017). "Having demonstrated that AR inhibition radiosensitizes multiple AR-positive breast cancer cell lines, we then evaluated the effect of AR inhibition in vivo." (PMID 28840192, 2017). "All together, these data suggest an interplay between C1orf64 and AR with significance in the biology of breast cancer." (PMID 28915724, 2017). "Recent attention has focused on the emerging roles of androgen receptor (AR) not only as a prognostic and predictive factor, but also as a therapeutic target in breast cancer patients." (PMID 29137314, 2017). "In breast cancer, the level of AR expression is positively correlated with ER and/or PgR expression, and high AR expression is an indicator of good prognosis in HR-positive breast cancer." (PMID 28060723, 2017). "A study examining treatment with AR antagonists in AR-expressing breast cancers is currently underway for clinical application." (PMID 28067809, 2017). "All together, these findings suggest that AR activation regulates the transcription of a number of AR co-expressed genes and has a profound repressive effect on C1orf64 expression in breast cancer cells." (PMID 28915724, 2017). "Given that AR-targeted therapies are under development, there is an urgent need to better understand the biology of AR in breast cancer." (PMID 28957377, 2017). "Ongoing clinical trials are evaluating anti-androgens and selective androgen receptor modulators across different breast cancer subtypes." (PMID 28643022, 2017). "In a comparison of ERα- and AR-positive breast cancer and paired local recurrences or solid distant metastases, AR expression is often maintained even when ERα-expression is lost." (PMID 28903441, 2017). "We characterized the radiation therapy response of 21 breast cancer cell lines and paired this radiation response data with high-throughput drug screen data to identify androgen receptor as a top target for radiosensitization." (PMID 28840192, 2017). "The current study is a comprehensive review of the available data regarding the pathophysiology of AR-positive breast cancer, and makes important efforts to discuss the nuanced differences between AR-positive breast cancers in relation to co-receptor status." (PMID 28245550, 2017). "We demonstrate significant correlation of AR RNA and protein expression levels across all subtypes of breast cancer." (PMID 28840192, 2017). "In breast cancer cell line T-47D, which is ERα- and AR-positive, treatment with the aromatase inhibitor exemestane was shown to result in increased HSD17B2 expression, a change which was associated with increased DHT expression." (PMID 28430630, 2017). "Signals generated by AR expression have been confirmed to display adverse effects on cellular proliferation in some breast cancer cell lines treated with 5-alpha-dihydrotestosterone." (PMID 28067809, 2017). "As FOXA1 is emerging as a critical player in breast cancer biology we examined the impact of its co-expression with AR and ERβ isoforms on survival in an ERα+ background." (PMID 28350011, 2017). "The function of AR depends largely on the level of co-expression of ERα in HR-positive breast cancer (i.e., luminal breast cancer)." (PMID 28245550, 2017). "Androgen and androgen receptor (AR) signaling has an important role in the initiation and progression of many hormone-related cancers including prostate and breast cancer." (PMID 28326012, 2017).